TNF (tumor necrosis factor)
Diseases named in the same sentence as TNF in open-access papers (continued):
Sharing a sentence is not in itself a finding about the gene and the disease.
cancer (continued). "For example, TNF-α inhibitors have been used to treat multiple auto-immune diseases, which also exhibit similar sickness behaviors to those seen in cancer patients." (PMID 37568698, 2023). "Costimulatory molecules, consisting of the B7-CD28 family and tumor necrosis factor (TNF) family, play a critical role in cancer biology." (PMID 36837389, 2023). "Our analysis indicated that TNF-α is a target for miR-939-5p, showing the greatest activity in G1 cancer, which then gradually declines." (PMID 37233761, 2023). "In total, 49 biological processes, five molecular functions and 61 metabolic pathways were similarly enriched for JQ1 and GSK2801 BC targets among which several terms are related to cancer: IL-17, TNF and JAK-STAT signaling pathways." (PMID 38213901, 2023). "In certain cancers that progress toward cachexia, the release of various cytokines, such as TNF-α, IL-6, and interferon gamma (IFN-γ), plays a significant role." (PMID 37755304, 2023). "In the early stage of CRLM, the adherence of disseminated cancer cells to KCs prompts KCs to capture and phagocytose the cancer cells and release TNF-α, interleukin-1α (IL-1α) and IL-1β, thus reducing the metastasis of colon cancer cells to the liver." (PMID 37480104, 2023). "Similar conclusions were drawn from KEGG analysis, which revealed that genes were primarily engaged in the pathways for NF-κB signaling, IL-17 signaling, TNF signaling, pathways in cancer, and JAK-STAT signaling." (PMID 38098990, 2023). "We found a similar positive correlation between LGALS3 and cancer-specific EMT signature scores in OVCA420 cells treated with either EGF (R2 = 0.01) or TNF-α (R2 = 0.02)." (PMID 38086828, 2023). "Another cytokine that plays an important role in cancer progression and immune exclusion is the pleiotropic cytokine TNFα." (PMID 37284199, 2023). "Over time, evidence also emerged to support some studies that showed TNF-α promoting cancer growth and progression." (PMID 37232720, 2023). "Our model uses cancer patients as features to predict the genes involved in the NFκB/TNF signaling pathway and can be adapted to predict the genes for different cancer types by switching the cancer type of patients." (PMID 37475016, 2023). "Increases in adipose tissue volume and macrophage influx result in higher levels of fever-inducing proinflammatory cytokines (TNF-α, IL-1β, and IL-6), already increased as a consequence of cancer." (PMID 37374212, 2023). "The primary pro-inflammatory cytokines related to the development of cancer cachexia are TNF-α, interleukin (IL)-1 beta, IL-6, epidermal growth factor (EGF), transforming growth factor (TGF)-β, and platelet-derived growth factor (PDGF)." (PMID 37571328, 2023). "The co-expression of TNFα with MMP-9 or cancer stem cell marker CD44 in metastatic RCC tumors increases the resistance to sunitinib treatment." (PMID 37190141, 2023). "In this study, we found that in the CaSki cells, AM significantly inhibited TNFα gene expression in a concentration-dependent manner, suggesting that this anti-inflammatory effect is part of the mechanisms involved in its anti-cancer activity." (PMID 36769377, 2023). "Increased levels of circulating IL-1 (cancer-promoting), IL-2, IL-2 receptors (IL-2R) (cancer-suppressive), IL-4, IL-8, IL-17 (cancer-promoting) and TNF-α have been reported in patients with SSc." (PMID 37681925, 2023). "Other factors that can modify the role of TNFα in cancer include caspase activation, the variable expression of adaptor proteins, and proteins from the Bcl-2 family." (PMID 36980727, 2023). "Hepatic macrophages are the primary cells responsible for the production of “cancer-promoting cytokines,” such as IL-6 and TNF-α, in response to LPS." (PMID 37896221, 2023). "It is well accepted that proinflammatory cytokines like TNF-α also correlated with development and/or progression of inflammation related cancers such as HCC." (PMID 37291206, 2023).
cancer (continued). "TNF-α plays a key role in inflammation and apoptosis of cancer cells through the tumor necrosis factor receptor 1 (TFNR1) signaling pathway." (PMID 38001420, 2023). "Based on the published data, further investigations are required to determine the effects of NSAIDs on the TNF-α release and cancer cell biology." (PMID 36765695, 2023). "It has also been shown that the high concentration of TNFα found in these patients correlates strongly with increased advancement of the cancer, a shortened survival period, and increased expression of IL-6." (PMID 36834426, 2023). "As for other cancers, indication for TNF-antagonists in IBD patients with a history of cancer requires a careful selection of patients in a multidisciplinary approach with oncologists." (PMID 37113615, 2023). "There is robust evidence that TNF-α is a crucial player in several human cancers, although with very discordant effects on different types of cancer." (PMID 36980727, 2023). "KEGG pathway enrichment analysis showed that FC exerted its therapeutic effects on UC by regulating IL-17 signaling pathway, TNF signaling pathway and Pathways in cancer." (PMID 37161415, 2023). "TNF-α is a trigger of the death receptor signal, which is necessary for immunity and anti-cancer effects through regulated cell death, especially in the presence of SM-facilitated apoptosis." (PMID 36831656, 2023). "DCs cocultured with FeMOF-based cancer vaccines show significantly higher cytokines secretion, such as interleukin (IL) -1β and tumor necrosis factor (TNF) -α, compared with free OVA and medium groups." (PMID 38259474, 2023). "In contrast, four of the six studies that compared tofacitinib and anti-TNF agents detected at least one case of cancer." (PMID 37190126, 2023). "Laboratory research on the impact of thiopental administration on TNF-α production in cancer cell biology is limited." (PMID 36765695, 2023). "RJ also reduced the bronchoalveolar lavage fluid levels of TNF-α in cancer and reduced cellular toxicity in patients treated with bleomycin." (PMID 36986201, 2023). "CD8+ T cells can also indirectly kill cancer cells by releasing cytokines such as tumor necrosis factor (TNF)." (PMID 38288118, 2023). "KEGG enrichment analysis of the RNA-seq data showed that YTHDC1 silencing upregulated many cancer-related pathways, including the Hippo, TNF, MAPK, VEGF, and PI3K-AKT-mTOR signaling pathways." (PMID 37258572, 2023). "Blocking TNF-α has emerged as a possible strategy to improve anti-cancer responses to ICI treatment as it is thought to enhance specific immune responses by limiting activation-induced cell death of cytotoxic T cells." (PMID 36803614, 2023). "Ferulic acid derivates represent a suite of promising cancer-preventive agents by blocking the release of inflammatory TNF-α and a series of pathways related to anti-inflammatory immune responses." (PMID 37190160, 2023). "ROCK can promote the production of TNFα via NF-κB activation, and fasudil treatment inhibits the activation of NF-κB and production of proinflammatory cytokines in inflammatory disease and cancer." (PMID 36864189, 2023). "TNFα, acting as a proinflammatory cytokine, can activate NF-κB, which leads to the transcriptional regulation of genes that are involved in cancer cell proliferation." (PMID 37371757, 2023). "In summation, according to the available data, perioperative RBC transfusion seems to influence the release of TNF-α and even cancer prognosis; however, further prospective trials are needed to build definitive evidence." (PMID 36765695, 2023). "In this review, inflammatory processes in cancer are discussed, focusing on cytokines IL-6, IL-10, and TNF-α, which play an important role in the inflammatory response, preventing or increasing different disorders, including cancer." (PMID 36771154, 2023).
cancer (continued). "Lim and coworkers have shown that CSN5, which is induced by nuclear factor kappa B (NF-κB) p50:p65 heterodimer (NF-κB p65), is required for tumor necrosis factor alpha (TNFα)-mediated stabilization of PD-L1 in cancer cells." (PMID 36902456, 2023). "In contrast, the absence of vagal nerve activity promotes tumor growth and reduces cell survival due to increased levels of TNF‐ α, which in turn promotes invasion and migration of cancer cells, one of the hallmarks of cancer pathology." (PMID 37587897, 2023). "It is believed that the interplay between signaling mediated by tumor necrosis factor-alpha (TNF-α) and ROS generated by myeloid cells plays a role in chronic inflammation, potentially promoting the onset of cancer." (PMID 37927596, 2023). "It should be noted that TNF-α can activate the canonical NF-κB pro-survival pathway in cancers, thus contributing to therapy resistance." (PMID 37917013, 2023). "Further GSEA suggested that cytotoxic T cells were significantly enriched in 2 cancer hallmarks and 9 immune signatures from MigDB and indicated to be active in response to tumor necrosis factor (TNF) with the regulation of NFKB." (PMID 37335089, 2023). "The genes identified by the model are likely involved in the NFκB/TNF-regulated pathways, particularly the canonical ones, and exert a significant influence on cancer progression and patient prognosis." (PMID 37475016, 2023). "The participation of TNF-TNFRs in cancer and inflammatory diseases is well-documented, and TNF-therapies directed to control their activity have been developed, but improved therapies are needed to be more effective and avoid undesirable side effects." (PMID 37735159, 2023). "Application of anthracycline anti-cancer drugs activated the TNF-alpha and adrenergic signaling pathways in cardiomyocytes." (PMID 37108624, 2023). "For example, the increased FES kinase in severe COVID‐19 can be addressed by repurposing Fostamatinib (a cancer drug) with the purpose of reducing organ damage via inhibition of TNF, IL‐8 and aggressive action of GM‐CSF." (PMID 36537107, 2023). "In particular, we have demonstrated that, contrary to the proven protective role of E2 in NF-κB activation and inflammation as seen in several diseases, in cancer, E1 cooperates with TNF-α to drive NF-κB activation, inflammation and tumourigenesis." (PMID 36674737, 2023). "TNF, an inflammatory cytokine, can activate the NF-κB signaling pathway by binding to its receptor TNF-R1 and plays an important role in cancer development and progression." (PMID 37400770, 2023). "Although limited by their retrospective design, these studies suggest that anti-TNF agents are safe in patients with previous cancer." (PMID 36831424, 2023). "Recently, in other cancers it was described that neutrophils can be activated to their full killing potential by supplementing IgG antibody therapy with TNF and CD40 agonists." (PMID 38087370, 2023). "Significant decrease in TNF-α and IL-6 in serum, beneficial effects on cancer-related fatigue and quality of life compared to placebo." (PMID 36969071, 2023). "ORM1 is an acute-phase protein whose levels increase rapidly under conditions of inflammation, stress, chronic diseases (cancer, etc.)and injury and can be modulated by glucocorticoids, TNF-α, IL-1, IL-8, IL-6, and IL-6-related cytokines." (PMID 37355563, 2023). "The pro-inflammatory cytokines IL-1β, IL-6, and IL-8 were two-fold elevated in contrast to TNFα, which appears to be a cytokine discriminating the inflammatory response in aging and cancer." (PMID 38003396, 2023). "NK cells and CD8 + T lymphocytes can also induce apoptosis in cancer cells by releasing Fas ligand (FasL), tumor necrosis factor (TNF)-α and interferon (IFN)-γ." (PMID 37221555, 2023).
cancer (continued). "(2020) evaluated that Rb1 can reduce the expression levels of key inflammatory cytokines TNF-α and IL-6 in a cancer cachexia mouse model, this finding is consistent with our experiment, indicating that Rb1 can alleviate symptoms caused by inflammation." (PMID 37868069, 2023). "SOR reduced the level of SOX-2 that maintenance of cancer stemness and tumorigenicity, and TNF-α and IL-1β levels." (PMID 37259369, 2023). "Beyond this, TNF-α contributes to cancer cachexia by fostering increased gluconeogenesis, adipose tissue loss, proteolysis, and reductions in protein and fat metabolism." (PMID 37755304, 2023). "Up until now, several functional SNPs within the TNF-α gene have been identified and described as cancer-related genetic alterations." (PMID 37533569, 2023). "Evidence from in vitro studies reported cell-protective effects of PCA through various mechanisms such as increased IkB degradation and consequent NF-kB activation in TNF-α-induced cell death of various cancer tissues." (PMID 37259418, 2023). "We encountered four cancer patients with CD and a history of anti TNF-α Ab therapy before being diagnosed with advanced anorectal cancer." (PMID 37185713, 2023). "NK cells are activated by recognizing virus invasion and cancer cells, and they induce immune responses by producing large amounts of TNF-α and IFN-γ." (PMID 37189708, 2023). "Although neutrophils have an anti‐inflammatory effect, they also secrete cytokines that promote cancer progression, such as interleukin and tumor necrosis factor α." (PMID 38069522, 2023). "In hepatic tumors, reciprocal influence between cancer cells and phagocytes has been demonstrated; TNF-α produced by TAMs induced EMT and stemness in liver tumor cells, the latter in turn promoted M2 macrophage polarization via the Wnt/β-catenin signaling." (PMID 36980226, 2023). "PPI network analysis identified 28 FC-UC hub genes that were mainly enriched in the IL-17 signaling pathway, the TNF signaling pathway, and pathways in cancer." (PMID 37161415, 2023). "Although the use of TNF-α blockade has not withstood patient-based clinical trials yet, the applications of anti-TNFα remain promising in preventing cardiotoxicity and allowing patients to continue cancer immunotherapy." (PMID 38136253, 2023). "TNF-α showed a low expression in cancer tissues than normal tissues and paracancerous tissues (P < 0.05)." (PMID 36865498, 2023). "Previous studies propose that TNF-alpha can induce apoptosis in cancer cells, and its role in different cancers, such as pancreatic and colorectal cancer, has been proved." (PMID 38077386, 2023). "Increased production of pro-inflammatory cytokines such as IL-1β, IL-6, TNF-α and MCP-1 has also been linked to various types of cancer." (PMID 37173732, 2023). "Proinflammatory cytokines, including IL-1, IL-6, and TNF-α, contribute to the pathology and progression of numerous diseases, such as inflammatory diseases and cancers." (PMID 36611025, 2023). "Peripheral blood mononuclear cells supernatant also showed increased levels of IL-6, IL-8, IL-10, IL-18, macrophage inflammatory protein 1 gamma (MIP-1γ) (cancer-promoting) and TNF-α (cancer-suppressive)." (PMID 37681925, 2023). "While our understanding of the pro-inflammatory cytokines, IL-6 and TNF-α leading to cancer cachexia has been established, the immunopathogenesis of muscle wasting has been overlooked." (PMID 37701438, 2023). "Many pro-inflammatory cytokines increase the concentration of TNFα and IL-6, which are the key cytokines in cancer progression." (PMID 36981858, 2023). "Because anti-TNFs are not recommended after a diagnosis of cancer, and because patients with previous cancers are excluded from clinical trials, the data on anti-TNF use in IBD patients with previous cancer are sparse." (PMID 36831424, 2023).
cancer (continued). "In summation, perioperative DEX treatment seemed to have a beneficial effect on anti-inflammation by reducing the expression of TNF-α and improved postoperative outcomes in patients receiving cancer surgery." (PMID 36765695, 2023). "It was found that tumor necrosis factor (TNF) was able to kill cancer cells in mice, and the TNFR signaling pathway was able to induce apoptosis." (PMID 37055846, 2023). "TNF-α, a common inflammatory cytokine with important roles in homeostasis and pathogenesis, works as a double-edged sword in cancer behaviour." (PMID 38041080, 2023). "Basic research on the impact of midazolam on the release of TNF-α in cancer cell biology is limited." (PMID 36765695, 2023). "Once the role of conditioned media with TNFα-treated preadipocytes in the creation of an inflammatory milieu was established, we analyzed the possible effect of this media on cancer epithelial behavior." (PMID 37107188, 2023). "TNF-α functions physiologically as a proinflammatory cytokine, responsible for innate immunity and surveillance against cancer." (PMID 36768732, 2023). "SMCs are a group of small molecules designed to antagonize inhibitor of apoptosis (IAP) proteins and sensitize cancer cells to death triggered by inflammatory cytokines, such as tumor necrosis factor α (TNFα)." (PMID 37040283, 2023). "Cancer cells release signaling molecules, including TNF-α and IL-6 that reprogram lipid metabolic pathways in CAAs surrounding tumors and in distal locations to trigger local and systemic lipolysis, causing adipose atrophy and cachexia in cancer patients." (PMID 37181035, 2023). "Based on the combined score of each interaction with 0.4 confidence, the top 3 significant cancer-related signaling pathways in association with HDAC6 were Akt1 (0.704), MAPK1 (0.584), and TNF (0.403)." (PMID 36639650, 2023). "The most significant pathways in the aging set were identified to be cytokine–cytokine receptor interaction, Epstein–Barr virus infection, transcriptional misregulation in cancer, NF-kappa B signaling pathway, and TNF signaling pathway." (PMID 37818088, 2023). "Studies have shown that IL-1β, TNF-α, and IL-6 are the most substantially changed cytokines in cancer, and their levels can even be related to cancer stage." (PMID 36627634, 2023). "γδ T cells are also early sources of IFN-γ and TNF-α, which inhibit cancer growth via enhancing antitumor immunity and inhibiting cancer angiogenesis." (PMID 37936711, 2023). "The causes of cancer malnutrition are not fully understood, and the role of cancer-inducing inflammatory cytokines such as IL⁃6 and TNF⁃α in its occurrence and development is gradually being recognized." (PMID 37533569, 2023). "In summary, RA seems to provide beneficial effects on surgical cancer patients, but further prospective trials are needed to investigate the impacts of RA on cancer progression by modulating perioperative TNF-α release." (PMID 36765695, 2023). "Constitutive activation of NF-kB has been shown in various types of cancer; NF-kB leads to a release of adhesion molecules and immune-regulatory cytokines (such as TNF-alpha, IL-1, IL-6 and IL-8), which converge leukocytes to sites of inflammation." (PMID 38332913, 2023). "Effector molecules such as CD25, IFN-γ, and TNF-α were then elevated in these treated cells, demonstrating enhanced cytotoxic activity and potential for pentanoate and C4 as supplements to cancer treatment for some malignancies." (PMID 37009485, 2023). "The mechanism of action is due to interferon-gamma (INF-γ), tumor necrosis factor-alpha (TNF-α), perforin, and granzyme-induced cell lysis acting by recognizing and binding to proteins or gangliosides on cancer cell surfaces." (PMID 38276666, 2023). "GSVA analysis indicated that high-SPP1 group was significantly associated with immune-related pathways such as PD-L1 expression and the PD-1 checkpoint pathway in cancer and the TNF signaling pathway." (PMID 38111044, 2023).